MSLN (mesothelin)
Diseases named in the same sentence as MSLN in open-access papers (continued):
Sharing a sentence is not in itself a finding about the gene and the disease.
colon carcinoma (10 papers, 2014 to 2025). "In this study, the reliability of serum mesothelin levels as a potential diagnostic and screening instrument was evaluated concerning colon cancer." (PMID 25477701, 2014). "MSLN-positive ovarian and colon cancer cells were used in vitro studies demonstrating markedly improved CAR-T cell activity with A2aR disruption, including increased cytokine generation and cytotoxicity." (PMID 40227616, 2025). "Mesothelin expression was significantly higher in gastric and colon cancer biopsies compared to normal tissues (p < .005)." (PMID 39548594, 2024). "Mesothelin expression in gastric and colon cancer cell lines ranged from 10 000 to 70 000 molecules per cell." (PMID 39548594, 2024). "GEPIA analysis was performed using human gastric (n = 408) and colon cancer tumours (n = 275) in TCGA database, to evaluate mRNA expression of mesothelin, compared to normal tissues." (PMID 39548594, 2024). "Our results are similar to previous studies that show variable effects of mesothelin expression on patient outcomes in gastric and colon cancers." (PMID 39548594, 2024). "To explore the association between mesothelin expression and prognosis of patients with gastric and colon cancers, we generated Kaplan–Meyer survival curves of patients with high and low MSLN expression based on the TCGA database for survival analysis." (PMID 39548594, 2024). "Our results show high expression of mesothelin mRNA in biopsies of patients with gastric and colon cancers, as compared with matched normal tissues." (PMID 39548594, 2024). "Taken together, these studies demonstrate that mesothelin is highly expressed in gastric and colon tumours as well as in cell lines, making them attractive candidates for mesothelin‐targeted CAR‐T cell therapies." (PMID 39548594, 2024). "Despite a link between MSLN positivity and aggressive colon cancer phenotype, the prognostic impact of MSLN expression appears to be low in many other tumor types." (PMID 33917081, 2021). "Right-sided MSLN-positive colon cancer patients had a significantly poorer prognosis (P < 0.0001); likewise, among the left-sided colon cancer patients, the MSLN-positive group tended to exhibit a poorer prognosis (P = 0.056)." (PMID 33196692, 2020). "Our data suggest that mesothelin exhibits effects towards colon cancer and serves as a biomarker for this deadly disease." (PMID 25477701, 2014). "In conclusion, we observed a continuous correlation between the serum mesothelin levels and tumor metastasis in colon cancer." (PMID 25477701, 2014). "The serum mesothelin levels were significantly higher in the patients with colon cancer than in the control group (P < 0.0001)." (PMID 25477701, 2014). "The serum mesothelin levels were measured with the ELISA kits and were evaluated in terms of significant difference when compared between colon cancer and control group." (PMID 25477701, 2014). "MSLN had been accepted to be a candidate biomarker in colon cancer." (PMID 31839813, 2019). "The valuation in the serum mesothelin levels, especially in patients with colon cancer, may have predictive potential and may also facilitate the development of treatment strategies for colon cancer patients." (PMID 25477701, 2014). "Mesothelin may behave as a clue reagent-marker of the intercellular pathway, leading to distant metastases and angiogenesis in colon cancer." (PMID 25477701, 2014). "This analysis of 95 colon cancer patients indicated that serum mesothelin levels might be of predictive value in colon cancer, especially in the analysis of the clinical stage." (PMID 25477701, 2014). "Additionally, the serum mesothelin levels were significantly higher in patients with colon cancer with increasing tumor size, lymph vascular involvement, distant metastasis, and lymph node metastasis (P < 0.001)." (PMID 25477701, 2014).
colon carcinoma (continued). "To validate our data analysis results, we extracted total RNA from patient colon cancer tissue and corresponding normal colon epithelial tissue and measured the mRNA expression levels of TIMP1, VEGFA, MYC, MSLN, EPHA2, ABHD2, and CD24." (PMID 38773226, 2024). "Under the same conditions, AmatuxEDV showed no binding to both MSTO-211H and murine colon carcinoma CT26 cells (MSLN negative cell line)." (PMID 29059207, 2017).
prostate carcinoma (10 papers, 2019 to 2025). A carcinoma that arises from epithelial cells of the prostate gland. "Among the prostate cancer models investigated in this study, 22Rv1-CR-1 was the only one expressing mesothelin at significant levels at the cell surface, which we recognize as a limitation of our study." (PMID 40427042, 2025). "In this study, we characterized mesothelin expression in prostate cancer and identified a relevant cancer cell line model for investigating mesothelin-targeted CAR-T therapy in this context." (PMID 40427042, 2025). "By performing a screen for proteins in pre-operative and post-operative serum from men with high-risk prostate cancer, we identified CASP8, MSLN, FGFBP1, ICOSLG, TIE2, and S100A4 proteins as candidate biomarkers for high-risk prostate cancer." (PMID 33828176, 2021). "We characterized MSLN expression in a panel of prostate cancer cell lines." (PMID 40427042, 2025). "MSLN, FGFBP1, ICOSLG, and TIE2 were also elevated in sera from patients with BPH, suggesting that MSLN, FGFBP1, ICOSLG, and TIE2 were not specific for high-risk prostate cancer." (PMID 33828176, 2021).
serous ovarian cancer (10 papers, 2008 to 2024). "Therefore, in our opinion, further studies with multiple cases of STIC, primary serous tubal carcinoma, and high-grade serous ovarian cancer associated with STIC or BRCA mutations should be investigated to clarify the role of MSLN in these malignancies and its impact on prognosis." (PMID 35565412, 2022). "Two successive rounds of selection were performed, first on recombinant MSLN protein and then on high-grade serous ovarian adenocarcinoma cell line OVCAR3." (PMID 37388728, 2023). "A phase I trial for infusion of anti-mesothelin CAR T cells in patients with recurrent serous ovarian cancer was shown to be feasible and safe." (PMID 34680456, 2021). "FRA, MSLN and MPF were all shown to be detectable in urine samples from both healthy women and women with serous ovarian cancer." (PMID 23590973, 2013). "The serum levels of FRA, MSLN, CA125 and HE4 readily discriminated between serous ovarian cancer and control serum samples, with p-values of <0.0001 for FRA, MSLN and CA125, and 0.0002 and 0.0012 for HE4 and MPF, respectively." (PMID 23590973, 2013). "We therefore intend to proceed with evaluation of MUC16, WFDC2, MSLN and MMP7, all of which have sensitivity >30% at 98% specificity in detection of clinically apparent serous cancers, beginning with analysis of serum specimens collected months to years prior to diagnosis of serous ovarian cancers." (PMID 18612378, 2008).
pleural mesothelioma (9 papers, 2014 to 2025). A neoplasm that arises from the mesothelial cells of the pleura. "We found 46 new cancer-associated proteins for pleural mesothelioma, and the presence of mesothelin and PD-L1/PD-L2 enriched in 100 K and 10 K EV, respectively." (PMID 37190292, 2023). "We reported previously that N-ERC/mesothelin could be a useful biomarker for the early diagnosis of pleural mesothelioma and developed an enzyme-linked immunosorbent assay (ELISA) system for its detection." (PMID 25045139, 2014). "BZT2312 is undergoing a pilot phase I clinical study, enrolling patients with MSLN-positive pleural mesothelioma (NCT06249256)." (PMID 41335396, 2025). "Soluble mesothelin is found in the blood and pleural fluid of patients with pleural mesothelioma and levels correlate with tumour stage and bulk." (PMID 38097208, 2024). "Soluble mesothelin has gained regulatory approval for monitoring of patients who are diagnosed with epithelioid or biphasic pleural mesothelioma, albeit in limited situations." (PMID 37190292, 2023). "Pembrolizumab is now being investigated with or without anetumab ravtansine (NCT03126630) in phase 1/2 research for mesothelin-positive pleural mesothelioma." (PMID 37469419, 2023). "Our results give preliminary evidence that PD-L1 and mesothelin are localized to specific subtypes of EVs in pleural mesothelioma, which warrants further investigation." (PMID 37190292, 2023). "Mesothelin and the programmed death ligand-1 (PD-L1) are the most widely reported biomarkers in pleural mesothelioma." (PMID 37190292, 2023). "Mesothelin is a cell surface protein that is expressed normally in mesothelial cells and is elevated in the serum of pleural mesothelioma patients, particularly for epithelioid subtype." (PMID 37190292, 2023). "We further validated the presence of two key pleural mesothelioma biomarkers, PD-L1 and mesothelin, via western blotting in each EV pellet across all cell lines." (PMID 37190292, 2023). "We therefore believe N-ERC/mesothelin is a useful biomarker in the clinical course of pleural mesothelioma from this aspect." (PMID 25045139, 2014). "We have previously reported that N-ERC/mesothelin is useful not only for diagnosis but also for monitoring chemotherapeutic response and for predicting prognosis in patients with pleural mesothelioma 26–28." (PMID 25045139, 2014). "As a next step, we should assess the combination of N-ERC/mesothelin with other biomarkers for pleural mesothelioma, by means of which patients suffering from this disease might obtain benefits throughout their clinical course." (PMID 25045139, 2014).
esophageal cancer (8 papers, 2015 to 2025). A primary or metastatic malignant neoplasm involving the esophagus. "A predicted MSLN amplification rate of 13% was seen for esophageal cancer (N = 185), which was mainly driven by the subset of esophageal adenocarcinomas with an MSLN amplification rate of 31% (N = 64)." (PMID 26172299, 2015).
serous carcinomas (8 papers, 2009 to 2025). "In a previous study, we observed that MSLN was overexpressed in OC, and overexpression (OE) was more significant in high-grade serous carcinoma (HGSC)." (PMID 35162954, 2022). "If the tumor type is considered in the hens with circulating mesothelin antibody, three out of the four (75%) were serous carcinomas." (PMID 21801396, 2011). "The mesothelin expression and OS of 59 ovarian high-grade serous adenocarcinoma were also analysed in this study." (PMID 19293794, 2009). "In addition, the expression levels of target genes CD74, MSLN, NaPi2b, and VEGF are higher in serous carcinoma than in mucinous, clear cell and endometrioid carcinoma." (PMID 40046734, 2025). "Then, we studied the MSLN protein expression across the different subtypes of EOC and found a significantly higher expression in serous cancer subtypes (including high and low-grade serous carcinomas)." (PMID 32612258, 2020). "Similar to the human expression pattern, 75% of the hen serous ovarian tumors had mesothelin gene expression, other subtypes had varying degrees of expression but to a lesser extent than serous carcinoma and none of the normal ovaries had detectable levels of mesothelin mRNA." (PMID 21801396, 2011).
cholangiocarcinoma (7 papers, 2017 to 2024). A carcinoma that arises from the intrahepatic biliary tree (intrahepatic cholangiocarcinoma) or from the junction, or adjacent to the junction, of the right and left hepatic ducts (hilar cholangiocarcinoma). "We show that rat activated portal fibroblasts, hepatic stellate cells, and cholangiocarcinoma cells express wild-type mesothelin and additional splice variants, while mouse activated hepatic stellate cells appear to only express wild-type mesothelin." (PMID 28898276, 2017).
leukemia (7 papers, 2019 to 2025). A malignant (clonal) hematologic disorder, involving hematopoietic stem cells and characterized by the presence of primitive or atypical myeloid or lymphoid cells in the bone marrow and the blood. "Interestingly, mesothelin promoted leukemia growth and was also associated with extramedullary disease in AML xenograft models." (PMID 35326701, 2022). "CAR-T cells targeting mesothelin were efficacious in controlling tumor burden by eradicating leukemia stem cells." (PMID 35326701, 2022). "Pre-clinical studies utilizing anti-mesothelin CAR-T cells, BiTEs, and anetumab ravtansine against mesothelin-expressing AML exhibit tumor-specific killing of leukemia cells, and the ability to reduce leukemic burden in vivo." (PMID 35326701, 2022). "Still more targets such as CLL-1, EGFR, NKG2D and mesothelin are being directed in CAR-T cell trials for leukemia and solid tumors." (PMID 31703740, 2019). "Mesothelin expression in leukemia stem cells suggests that similar to solid tumors, mesothelin may play a role in leukemia progression and relapse." (PMID 35326701, 2022).
lymph node metastasis (7 papers, 2014 to 2025). "In the MPM regional lymph node metastasis stage (N stage), N0 subgroup showed that the higher the MSLN gene expression level, the longer the patient survival time, and the significant difference in the survival time distribution of the subgroups." (PMID 36140611, 2022). "A few articles reported some prognostic factors of patients with malignant cancers, including age, gender, asbestos exposure, lymph node metastases, estrogen receptors, mesothelin, GLUT1, morphological growth patterns, and the mitotic index." (PMID 29506546, 2018). "The serum mesothelin levels were significantly correlated with distant metastasis, lymph node metastasis, and lymph vascular involvement (P = 0.004, P = 0.005, and P = 0.003)." (PMID 25477701, 2014). "MSLN expression correlated with slightly older age at diagnosis, but not with race, tumor size, histologic or nuclear grade, LVI or lymph node metastases." (PMID 25506917, 2014). "In the WCMC cohort, comprising castration-resistant tumors, elevated MSLN expression was observed in 6.6% (1/15) of the CRPC-Neuroendocrine cases, and in 3% (1/34) of the CRPC-adeno cases, this later corresponding to one case of lymph node metastasis." (PMID 40427042, 2025).
lymphoma (7 papers, 2016 to 2025). A malignant (clonal) proliferation of B- lymphocytes or T- lymphocytes which involves the lymph nodes, bone marrow and/or extranodal sites. "To assess the impact of combination therapy on various tumors and lymphomas, we categorized them based on six major tumor-associated antigens: mesothelin, disialoganglioside GD-2, CD-19, CD-22, CD-133, and CD-30, which are present in different tumor types." (PMID 38799440, 2024). "To see the impact of combination therapy on different tumors and lymphomas, we categorized them based on six major tumor-associated antigens: mesothelin, disialoganglioside GD-2, CD-19, CD-22, CD-133, and CD-30, which are present in various tumors." (PMID 38799440, 2024). "BiAbs targeting CD47xCD19 or CD47xMSLN were tested in immunodeficient mice implanted with the following human tumor cell lines: Raji (CD19+, lymphoma), OVCAR-3 (MSLN+, ovarian) or MSLN-transfected HepG2 (hepatic)." (PMID 30400822, 2018). "A number of murine cell lines did not express mesothelin, including: P815 mastocytoma, YAC-1 and EL4 T lymphomas, B16-F10 melanoma (not shown), Lewis lung carcinoma, the J774 macrophage/monocyte cell line." (PMID 26931187, 2016).
multiple myeloma (7 papers, 2020 to 2025). "As a model, we utilized the RPMI 8226 multiple myeloma cell line, which lacks expression of mesothelin and CD19 and has moderate expression levels of MUC1." (PMID 41372740, 2025). "Like multiple myeloma, trogocytosis-mediated surface antigen loss poses a significant barrier to effective CAR T cell therapy of MSLN-positive solid tumors, as expression pattern of MSLN is naturally heterogeneous and trogocytosis may additionally downregulate its expression." (PMID 37974170, 2023).
peritoneal mesothelioma (7 papers, 2007 to 2025). A benign or malignant mesothelial neoplasm that arises from the peritoneum. "Tumour markers such as CA-125, CA15-3, mesothelin and osteopontin may be elevated in patients with peritoneal mesothelioma." (PMID 34817720, 2021). "Serum mesothelin may be a useful test to monitor treatment response in mesothelin-expressing cancers, because after surgery there is a rapid decrease in mesothelin levels in patients with peritoneal mesothelioma." (PMID 19384429, 2007).
thymic carcinoma (7 papers, 2017 to 2025). Thymic carcinoma (TC) is a type of thymic epithelial neoplasm characterized by a high malignant potential. "Mesothelin is a cell surface protein whose high expression has been observed in thymic carcinoma, as well as in other malignancies, such as mesothelioma, ovarian cancer, and gastrointestinal tumors." (PMID 41300989, 2025). "Mesothelin is expressed in the majority of thymic carcinomas, and several mesothelin-directed treatments are under development, including CAR-T therapy." (PMID 38611047, 2024). "For thymic carcinoma, the novel biomarkers of MSLN, CCL20, and SLC1A5 are identified and observed an elevated expression of LAG3 and HAVCR2 in malignant tumorn‐infiltrating mature T cells." (PMID 39258580, 2024). "Mesothelin is a cell-surface glycoprotein with high frequencies of expression in several cancers, including up to 79% of thymic carcinomas, but with limited expression in normal tissues." (PMID 38611047, 2024). "Anetumab ravtansine, an anti-mesothelin antibody conjugated to a tubulin inhibitor, is currently being evaluated in a variety of mesothelin-expressing tumors, including thymic carcinoma (NCT03102320)." (PMID 35565190, 2022). "Forty-one percent of thymic carcinomas were positive for mesothelin on the cell membrane with MN-1 antibody." (PMID 28460459, 2017). "In vitro and in vivo models have suggested that a new antibody-drug-conjugate named anetumab ravtansine that targets mesothelin could be a potential targeted therapy for the treatment of thymic carcinoma." (PMID 41300989, 2025). "Mesothelin immunohistochemistry may also assist in the differential diagnosis of thymoma versus thymic carcinoma." (PMID 28460459, 2017). "While the use of mesothelin-directed CAR T-cell therapy has been explored in patients with solid tumors, its role in the treatment of thymic carcinomas is yet to be evaluated." (PMID 35565190, 2022). "Bcl-2, calretinin, CD5, CD117, CEA, GLUT1, IGF-1R, mesothelin, MOC31, MUC1, and p21 were higher expressed in thymic carcinomas." (PMID 35565429, 2022). "Strong cell surface expression of mesothelin is frequently observed in thymic carcinomas, but only infrequently in thymomas, and is absent in thymic neuroendocrine tumors." (PMID 35565190, 2022).
anaphylaxis (6 papers, 2015 to 2025). An acute hypersensitivity reaction that occurs from exposure to an allergen. "In another clinical trial, the development of anti-CAR immune responses led to the development of anaphylaxis in a patient after receiving several individual doses of anti-mesothelin CAR T cells derived from a murine anti-human mesothelin scFv." (PMID 32391013, 2020). "Another potential side effect of repeated administration of CAR T-cells has been observed in a previous clinical study where patients receiving T-cells electroporated with anti-mesothelin mRNA CAR bearing a mouse anti-human scFv experienced anaphylaxis from the development of anti-mouse antibodies." (PMID 27907031, 2016). "In this line, multiple infusions of mesothelin-specific RNA CAR T cells were reported to lead to clinical anaphylaxis in a single patient, although the mechanism was believed to involve IgE antibodies specific to the murine CAR utilized rather than off-tissue effects from targeting FRα mesothelin." (PMID 26359629, 2015).